SIRT3 (sirtuin 3)
Diseases named in the same sentence as SIRT3 in open-access papers (continued):
Sharing a sentence is not in itself a finding about the gene and the disease.
cardiomyopathy (20 papers, 2016 to 2025). A disease of the heart muscle or myocardium proper. "Enhanced NLRP3 inflammasome activation is associated with aggravated mitochondrial damage, in conditions of Sirtuin 3 (SIRT3) deficiency, which is protective against mitochondrial dysfunction, especially in diabetic mice with cardiomyopathy." (PMID 40507468, 2025). "In conclusion, our results suggest that the myocardial remodeling and cardiac function decline in ISO-induced cardiomyopathy model rats may be associated with down-regulation of SIRT3 and PGC-1α expression." (PMID 32153406, 2020). "We also found that SIRT3 levels are reduced in patients with DOX-induced cardiomyopathy, as compared to control patients." (PMID 37566283, 2023). "In summary, the present study reveals that melatonin treatment significantly improves heart cardiac function and slows cardiac fibrosis from DOX-induced cardiomyopathy by activating the Sirt3/TFEB axis." (PMID 37760018, 2023). "In the context of FA, SirT3 has been studied in two conditional mouse models that develop a fatal cardiomyopathy and impaired activity in respiratory complexes." (PMID 38129330, 2023). "It has previously been reported that increased NAD+ levels in a FA cardiomyopathy model improved cardiac function in a SirT3-dependent manner." (PMID 38129330, 2023). "Honokiol preserves mitochondrial function and protects the heart from doxorubicin-induced cardiomyopathy in mice in a SIRT3-dependent manner." (PMID 34202229, 2021). "In this study, we established a rat model of isoproterenol (ISO)-induced cardiomyopathy to investigate the potential mechanism of PER in improving cardiac protection through the SIRT3/PGC-1α pathway." (PMID 32153406, 2020). "In this study, we report that HKL, an activator of SIRT3 can mitigate doxorubicin-induced cardiomyopathy in mice." (PMID 28423723, 2017). "In summary, MST1 contributes to DOX-induced cardiomyopathy through SIRT3 downregulation." (PMID 37566283, 2023). "Additionally, growing studies have identified that SIRT3 plays a critical protective role in DOX-induced cardiomyopathy." (PMID 36691640, 2023). "Since fibrosis and inflammation are crucial during the development of these cardiomyopathies, our data suggest that SIRT3 may be useful for treating these conditions." (PMID 32296036, 2020). "Among the sirtuin family members, SIRT1, SIRT3 and SIRT6 have attracted much attention as the potential cardioprotective modulators against inflammation, vascular remodelling, cardiomyopathy and the development of atherosclerotic plaques." (PMID 38894630, 2024). "It was previously demonstrated that SIRT3 is downregulated in response to DOX treatment, thereby promoting the development of cardiomyopathy." (PMID 37566283, 2023). "In line with the data from previous studies, we showed that melatonin administration increased Sirt3 expression and protected hearts in a chronic DOX-induced cardiomyopathy model." (PMID 37760018, 2023). "Collectively, our results suggest that PER induces mitochondrial biosynthesis-mediated enhancement of SIRT3 and PGC-1α expression, thereby improving the cardiac function in rats with ISO-induced cardiomyopathy." (PMID 32153406, 2020). "In mitochondria, SirT3 is the main NAD+-dependent deacetylase, and SirT3 inhibition and protein hyperacetylation have a negative feedback effect contributing to cardiomyopathy in FA." (PMID 38129330, 2023). "NMN improves cardiac function in a SIRT3-dependent manner in an FRDA cardiomyopathy model, whereas NR does not." (PMID 32411700, 2020). "Furthermore, in a model of cardiomyopathy, NMN treatment restored cardiac function by activating SIRT3." (PMID 31823815, 2019). "Therefore, to test whether Sirt3 is a key factor in protection, Sirt3 knockout mice were used, and it was found that the protective effects of melatonin in DOX-induced cardiomyopathy were partly abolished." (PMID 37760018, 2023).
oral cancer (20 papers, 2011 to 2023). "The presence of miR-31-mediated post-transcriptional regulation of SIRT3 in OSCC has been associated with OSCC progression, the oxidative stress in oral cancer being increased by SIRT3-miR-31 targeted to suppress mitochondrial activity." (PMID 35456400, 2022). "In OSCC, the posttranscriptional regulation of SIRT3 is induced by miR-31, which targets the SIRT3 to destroy the mitochondrial structure and increase the oxidative stress response in oral cancer." (PMID 39282225, 2023). "Compound BZD9Q1, as a SIRT3 inhibitor, elicits cytostatic effects by inducing cell cycle arrest in the G2/M phase to show promising anti-cancer properties against oral cancer." (PMID 35832551, 2022). "In another study, EGCG showed different pro-oxidative effects on normal and oral cancer cells, which was correlated with a different regulation of the sirtuin (SIRT)-3 pathway." (PMID 31817990, 2019). "For example, SIRT3 expression was found significantly higher in oral cancer cell lines and human oral cancer samples than in normal control." (PMID 23230084, 2012). "The high expression levels of SIRT3 in OSCC tissues compared with normal tissues further supported a role for SIRT3 in oral cancer carcinogenesis." (PMID 21472714, 2011). "The current investigation revealed a novel role for SIRT3 in oral cancer carcinogenesis as a promoter of cell proliferation and survival, thus implicating SIRT3 as a new potential therapeutic target to treat oral cancer." (PMID 21472714, 2011). "In summary, our findings reveal a novel role for SIRT3 in oral cancer carcinogenesis as a modulator of cell proliferation and survival, supported by in vitro and in vivo data." (PMID 21472714, 2011). "The overexpression of SIRT3 in oral cancers suggests its potential as a therapeutic target." (PMID 38203666, 2023). "A study conducted by Ling Tao also showed that the green tea catechin (–)-epigallocatechin-3-gallate (EGCG) appears to be a promising medicine because it inhibits SIRT3 activity in oral cancer cells but activates SIRT3 in normal cells (Tao, Park & Lambert, 2015)." (PMID 36815979, 2023). "Furthermore, miR-31 directly targets SIRT3 to activate oxidative stress by disrupting mitochondrial activity in oral carcinoma." (PMID 35832551, 2022). "One of the latest research also showed a new duty for SIRT3 in oral carcinogenesis as a promoter of cell proliferation and survival, therefore suggesting SIRT3 as a novel possible therapeutic objective to treat oral cancer." (PMID 33705642, 2021). "However, another study showed that Sirt3 acts as promoter of cell proliferation and survival in oral cancer carcinogenesis and that down-regulation of Sirt3 increased sensitivity of oral squamous cell carcinoma cell lines to radiation and cisplatin treatments." (PMID 32698385, 2020). "Increased expression of SIRT3 was found in oral cancer and melanoma." (PMID 28423723, 2017). "This implicates SIRT3 as a new potential therapeutic target for treating oral cancer." (PMID 21472714, 2011). "On the other hand, some studies have shown that SIRT3 may act as an inhibitor of oral cancer cells." (PMID 36815979, 2023). "Similar to SIRT1, SIRT3 may function as either an oncogene or suppressor in oral cancer." (PMID 36815979, 2023). "It has also been reported that RIP plays a shuttling role between survival and death signaling pathways to mediate anoikis in oral cancer, revealing that SIRT3 regulates anoikis in oral cancer through a potential negative correlation with RIP." (PMID 37667281, 2023). "To confirm that ZEB1 could physically bind to the SIRT3 and COX10 promoter regions in oral cancer cells, we conducted ChIP and Dual-luciferase reporter assays." (PMID 35963855, 2022). "Then, as an important mitochondrial redox modulator, sirtuin 3 (SIRT3) and its downstream targets (including GSH and SOD) transcription could be inhibited through decreasing the nuclear localization of the estrogen-related receptor α (ERRα) by EGCG in oral cancer cells." (PMID 31652732, 2019).
ischemic stroke (19 papers, 2017 to 2025). A stroke disorder caused by obstruction of blood flow to the brain, due to thrombotic (local blood clot formation) or embolic (due to a blood clot or other material traveling from another site) event. "First, Sirt3 was depressed by brain post-ischemic injury, and reduced Sirt3 expression was associated with an augmented infarction size in the brain, suggesting that Sirt3 is an endogenous protector against ischemic stroke." (PMID 37705748, 2023). "Altogether, these findings suggest that SIRT1 improves mitochondrial respiratory function by enhancing SIRT3 activity, which may illuminate the mechanism underlying the promotion of energy metabolism in treating ischemic stroke." (PMID 38767771, 2024). "This suggests that SIRT3 may contribute to the treatment of nerve damage caused by an ischemic stroke." (PMID 36374406, 2023). "As for ischemic stroke, SIRT3 exerted a protective effect by regulating the HIF-1α/VEGF pathway in astrocytes." (PMID 40969935, 2025). "This study establishes the irisin/SIRT3 as a novel therapeutic target for ischemic stroke, providing mechanistic insights for future interventions." (PMID 40235548, 2025). "In general, intervention studies validated the therapeutic potential of SIRT3 for ischemic stroke, but it is still necessary to explore its targeting ability and provide new directions for clinical treatment." (PMID 40969935, 2025). "In contrast, the overexpression of Sirt3 in vivo reduced the infarction size and played a protective role in ischemic stroke." (PMID 39844858, 2024). "Likely, the deacetylation regulated by Sirt3 is critical for protecting mitochondrial function and preventing neuronal death in ischemic stroke." (PMID 39844858, 2024). "Second, overexpression of Sirt3 restored neural viability by normalizing mitochondrial homeostasis, indicating that Sirt3 prevents ischemic stroke by protecting mitochondria." (PMID 37705748, 2023). "On the basis of our results, augmentation of Sirt3 expression and activation of the UPRmt are encouraging medicative tool for ischemic stroke." (PMID 37705748, 2023). "During the acute phase of ischemic stroke, the levels of HIF-1α and VEGF proteins in SIRT3-deficient mice increased, resulting in more severe BBB damage." (PMID 37627275, 2023). "Animal experiments have demonstrated mitochondrial biogenesis regulated by SIRT3 in haemorrhagic and ischaemic stroke; however, further studies are required to confirm its role in other types of brain injury." (PMID 37009480, 2023). "Here, we present the current research available on SIRT3 as a target for treating ischaemic stroke, subarachnoid haemorrhage, traumatic brain injury, thus highlighting the therapeutic potential of SIRT3 as a potent mediator of catastrophic brain injury." (PMID 37009480, 2023). "Using the same model of ischemic stroke, another study reported the protective effects of adjudin, a Sirt3 activator." (PMID 36675125, 2023). "According to in vivo and in vitro studies, SIRT3 deletion can worsen brain inflammation and blood-brain barrier damage after ischaemic stroke." (PMID 37009480, 2023). "Middle cerebral artery occlusion (MCAO)-induced ischemic stroke has been shown to be exacerbated in Sirt3−/− mice." (PMID 36675125, 2023). "The activation of the Akt-SIRT3-SOD2 pathway by melatonin as well as the increase in SIRT3 expression alone by it are mechanisms by which melatonin can decrease infarct volume and apoptotic rate after an ischemic stroke." (PMID 37891922, 2023). "Sirt3 plays important roles in the inhibition of neuroinflammation and protecting blood–brain barrier integrity in ischemic stroke." (PMID 36131290, 2022). "The role of SIRT3 in microglial cell migration and invading macrophages in ischemic stroke was studied." (PMID 32380741, 2020).
ischemic stroke (continued). "After transient middle cerebral artery occlusion (tMCAO) in adult male SIRT3 KO and wild-type (WT) mice, it was found that the level of SIRT3 in infarct region is decreased after ischemic stroke." (PMID 32380741, 2020). "Previous studies have demonstrated that Sirt3 is downregulated in infarct region of ischemic stroke." (PMID 31729962, 2019). "It has been reported that Sirt3 is a critical regulator in cellular protection, which contributes to neurovascular recovery in ischemic stroke." (PMID 31729962, 2019). "Here, we first reported PPAR-γ as a novel mediator of Sirt3 that together inhibit endothelial cell permeability and ischemic stroke." (PMID 31729962, 2019). "We have demonstrated that SIRT3 protects the brain from ischemic stroke by modulating superoxide dismutase 2 (SOD2) and the forkhead box O3a (FoxO3a)." (PMID 31208274, 2019). "In summary, we present an interesting mechanism that reveals new therapeutic targets for PPAR-γ and Sirt3 for ischemic stroke and provided new ideas for further research." (PMID 31729962, 2019). "Also, SIRT3 protects the integrity of the blood-brain barrier (BBB) in ischemic stroke mice by regulating the HIF-1α/VEGF pathway in astrocytes, reducing inflammatory responses and neuronal apoptosis." (PMID 40969935, 2025). "Collectively, these data reveal that SIRT1 alleviates the CI/R-induced damage to the mitochondrial ultrastructure by enhancing SIRT3 activity and may have therapeutic potential for reducing mitochondrial structural damage from ischemic stroke." (PMID 38767771, 2024). "Collectively, these findings evidence that the function of mitochondria is crucial in alleviating CI/R-induced neuronal damage and that the “SIRT1/SIRT3 acetylation and SIRT3 activity” may be exploited for the treatment of ischemic stroke." (PMID 38767771, 2024). "The proposed “SIRT1/SIRT3 activity” may highlight a novel therapeutic perspective for the clinical management of ischemic stroke-related conditions." (PMID 38767771, 2024). "SIRT3 plays an important role in the regulation of ischemic stroke processes." (PMID 37627275, 2023). "SIRT3 performs a dual function in ischaemic stroke as demonstrated in the current study." (PMID 37009480, 2023). "Thus, the UPRmt protects neural viability and mitochondrial homeostasis, and the Sirt3/Foxo3/Sphk1 pathway is a promosing therapeutic candidate for ischemic stroke." (PMID 37705748, 2023). "In ischaemic stroke, subarachnoid haemorrhage, traumatic brain injury, and intracerebral haemorrhage, SIRT3 is closely related to mitochondrial homeostasis and with the mechanisms of pathophysiological processes such as neuroinflammation, oxidative stress, autophagy, and programmed cell death." (PMID 37009480, 2023). "Melatonin plays a vital role in haemorrhagic and ischaemic strokes via the SIRT3 pathway." (PMID 37009480, 2023). "Together, our results suggested that SIRT3 may serve as a potential novel target for treatment of ischemic stroke." (PMID 36012382, 2022). "Based on our findings, we hypothesized that NBP derivatives, which showed better blood-brain barrier crossing capability and retained the enhancing effects on SIRT3, might be considered as promising drug candidates for ischemic stroke." (PMID 36012382, 2022). "We studied the role of Sirtuin 3 (SIRT3) in microglial cell migration in ischemic stroke." (PMID 31208274, 2019). "Taken together, this research not only demonstrated PPAR-γ might benefit to the growth of endothelial cell though activating Sirt3 but also indicated its potential value in the treatment for ischemic stroke." (PMID 31729962, 2019). "However, the detailed biological function of Sirt3 is still not fully understood in ischemic stroke and its molecule network still needs to be further investigated." (PMID 31729962, 2019). "In conclusion, our results indicate that PPAR-γ may improve endothelial cell permeability and ischemic stroke through inhibiting the expression of Sirt3." (PMID 31729962, 2019).
ischemic stroke (continued). "Furthermore, Sirt3 was demonstrated to be a crucial mediator of adjudin's inhibitory effect in the formation of glial scar and neuroprotective role following ischemic stroke." (PMID 29311941, 2017). "In addition, Sirt3-Foxo3a pathway mediates the neuroprotective effect of ketones in ischemic stroke." (PMID 29311941, 2017). "Furthermore, we reported that Sirt3-Foxo3a and Sirt3-Notch1 signaling pathways mediated the inhibitory effect of adjudin against astrocyte activation and glial scar formation following ischemic stroke." (PMID 29311941, 2017). "SIRT3 activators that could improve ischemic stroke found in nearly a decade." (PMID 40969935, 2025). "Collectively, these findings evidence that SIRT1 may provide neuroprotection against CI/R-induced oxidative stress by enhancing SIRT3 activity, signifying that a proper manipulation of “SIRT1/ SIRT3 activity” may alleviate the excessive oxidative stress in ischemic stroke." (PMID 38767771, 2024). "In addition, SIRT3 can aid neurovascular recovery in an ischaemic stroke model." (PMID 37009480, 2023). "SIRT3 helps in relieving brain edema and BBB damage after ischemic stroke, which might be achieved by increasing TJ proteins ZO-1 and Occludin by regulating the HIF-1α signaling pathway." (PMID 37627275, 2023). "Interestingly, some front-line drugs for ischemic stroke, including clopidogrel, aspirin and dl-3-n-butylphthalide (NBP), also rescued SIRT3 and reduced OGD/R-induced endothelial injury, suggesting that the recovery of SIRT3 expression was critical for the protection of these drugs." (PMID 36012382, 2022). "Thus far, a possible role of SIRT3 has been investigated only for neuronal and astrocytic SIRT3 in ischemic stroke, but has not been explored in endothelial cells." (PMID 36012382, 2022).